MYOCOS (myocilin opposite strand)
Gene: Protein-coding gene on chromosome 1 (171,600,621 to 171,638,799, forward strand). Ensembl gene ENSG00000283683.
Homologues: Orthologues: macaque MYOCOS (88% identical), rabbit MYOCOS (61% identical), dog MYOCOS (60% identical).